EGFR (epidermal growth factor receptor)
Diseases named in the same sentence as EGFR in open-access papers (continued):
Sharing a sentence is not in itself a finding about the gene and the disease.
acute myeloid leukemia (69 papers, 2010 to 2026). Acute myeloid leukemia (AML) is a group of neoplasms arising from precursor cells committed to the myeloid cell-line differentiation. "KEGG analysis indicated an abundance in pathways such as the PI3K/AKT signaling cascade, acute myeloid leukemia, hepatitis B, and resistance to EGFR tyrosine kinase inhibitors." (PMID 41158757, 2026). "The KEGG enrichment analysis showed that the hub genes had significant enrichment in EGFR tyrosine kinase inhibitor resistance, Hepatitis B, Acute myeloid leukemia, and Proteoglycans in cancer pathway." (PMID 40380246, 2025). "KEGG analysis revealed notably enriched pathways, including PI3K-AKT, MAPK, Ras, JAK-STAT, acute myeloid leukemia, EGFR tyrosine kinase inhibitors, and endocrine resistance." (PMID 40520175, 2025). "In preclinical studies, NKCEs have been used effectively in CD33+ acute myeloid leukaemia and myelodysplastic syndromes, epidermal growth factor receptor (EGFR) in multiple cancers, B cell maturation antigen (BCMA) in multiple myeloma, etc." (PMID 36797782, 2023). "Moreover, another study demonstrated that one-third of human acute myeloid leukemia (AML) patients express EGFR, which is associated with poor clinical outcome." (PMID 27806094, 2016). "In acute myeloid leukemia (AML), GLUT3 negatively regulates epidermal growth factor receptor (EGFR) activity and its downstream signaling pathways, contributing to tyrosine kinase inhibitors (TKIs) chemoresistance." (PMID 40264038, 2025). "In acute myeloid leukemia (AML), epidermal growth factor receptor (EFGR) is overly expressed on malignant cells, which can be easily targeted by an anti-EGFR antibody." (PMID 37629007, 2023). "The YTHDF2 encoding gene was found to be overexpressed and responsible for development of acute myeloid leukemia (AML), whereas it turned into a tumor suppressor by targeting EGFR, IL11 and SERPINE2 mRNAs for degradation in hepatocellular carcinoma." (PMID 33658012, 2021). "In approximately 15% of patients with acute myeloid leukemia (AML), total and phosphorylated EGFR proteins have been reported to be increased compared to healthy CD34+ samples." (PMID 34650910, 2021). "Two independent studies have reported that the combined use of 1,25(OH)2D3 with different tyrosine kinase inhibitors (TKIs)—gefitinib/erlotinib (epidermal growth factor receptor (EGFR) inhibitors) and sunitinib (multi-target TKI)—induces differentiation of acute myeloid leukemia cells." (PMID 28124999, 2017). "EGFR, KIT, and FLT3 mutants are well known as major oncogenic drivers of lung adenocarcinoma (LAD), gastrointestinal stromal tumor (GIST)/mast cell leukemia (MCL), and acute myeloid leukemia (AML), respectively." (PMID 38679330, 2024).
rectal cancer (69 papers, 2005 to 2026). A primary or metastatic malignant neoplasm that affects the rectum. "As a proof-of-concept, the influence of KRAS mutation-mediated resistance to EGFR-targeted therapy using cetuximab was tested in rectal cancer organoids." (PMID 33816288, 2021). "The epidermal growth factor receptor (EGFR) is over-expressed in approximately 60% of rectal cancers and associated with worse prognosis." (PMID 28859058, 2017). "The influence of EGFR pathway mutations on cetuximab-containing rectal cancer preoperative chemoradiation (CRT) is uncertain." (PMID 28859058, 2017). "Using the sensitive technology of NGS, comparing biopsy with resection, we describe for the first time substantial loss and gain of EGFR pathway mutations (mainly KRAS) in locally advanced rectal cancer undergoing pre-operative CRT." (PMID 28859058, 2017). "KRAS oncogene mutations (MUTKRAS) drive resistance to EGFR inhibition by providing alternative signaling as demonstrated in colo-rectal cancer." (PMID 26799287, 2017). "In conclusion, our experience from predictive testing for KRAS mutations reveal a high mutation frequency (67%) in rectal cancers from females and thus implicates that this subset is the least likely to respond to anti-EGFR therapies." (PMID 19832985, 2009). "While we demonstrated for the first time that circulating EGFR could be used as a potential biomarker for predicting pCR in rectal cancer, circulating EGFR has been associated with response to therapy in several types of cancer." (PMID 34298853, 2021). "The mRNA expression of the four HER family members has previously been assessed from a series of 100 locally advanced rectal cancers treated with radiotherapy or radiochemotherapy and showed an association for EGFR (ERBB1) and HER3 gene expression with development of distant metastases in LARC." (PMID 27610130, 2016). "Higher miR-592 expression has been shown to be associated with improved OS in patients receiving salvage anti-EGFR treatment and higher miR-196b-5p expression has been linked to response to neo-adjuvant 5-FU and radiotherapy in patients with locally advanced rectal cancer." (PMID 25329796, 2014). "It has been suggested that EGFR polymorphisms as well as polymorphisms of other genes active in the EGFR pathway may be potential indicators of radiosensitivity in patients with rectal cancer treated with chemoradiation." (PMID 19356222, 2009). "Nevertheless, the potential of introducing routine EGFR immunohistochemistry as a diagnostic tool into the clinical practice of rectal cancer management still has to be undertaken, and may allow clinicians to deliver targeted therapies even in patients with a poorer prognosis." (PMID 15967033, 2005). "The analysis highlighted significant involvement of VEGFR and EGFR signaling, both critical in tumor growth, angiogenesis, and immune modulation in rectal cancer." (PMID 41550766, 2026). "Mutations in the RAS genes significantly influence the management of metastatic rectal cancer, particularly in determining the potential success of anti-EGFR therapy." (PMID 40731762, 2025). "EGFR has been shown to be a key molecule in the pathogenesis of rectal cancer, and its expression in the tumor of LARC patients undergoing neoadjuvant therapy was associated with significantly lower DFS." (PMID 36900260, 2023). "KRAS mutation status is a predictor of poor response to anti-EGFR antibody therapy in metastatic CRC, and its correlation with rectal cancer response to CRT has been widely studied although a consensus was not reached." (PMID 35860583, 2022). "Subgroup analysis of OS based on primary tumour locations and sequences of anti-EGFR treatment was also performed in all mCRC patients and the subpopulation of middle/low rectal cancer patients." (PMID 34188197, 2021). "The expression level of EGFR and the activity of intracellular signalling components in rectal cancers influence the odds for a complete response to current treatments." (PMID 34321074, 2021).
rectal cancer (continued). "More recently, internalization of epidermal growth factor receptor (EGFR) by Rab5C was suggested to enhance resistance to ionizing radiation in rectal cancer." (PMID 32365785, 2020). "Colo-rectal cancer cells with MUTKRAS treated with anti-EGFR monoclonal antibodies are able to escape growth inhibition by several mechanisms, including MUTRAS." (PMID 26799287, 2017). "A study in Iran on locally advanced rectal cancer has shown the expression of EGFR functions as a predictor of response to treatment in these tumors." (PMID 25685149, 2015). "Epidermal growth factor receptor (EGFR) is overexpressed in 50–70% of primary rectal cancers and is related to decreased pathological complete response (pCR), disease-free survival (DFS), and overall survival (OS)." (PMID 25861256, 2015). "Second, elevated levels of EGFR expression are an independent adverse prognostic factor in rectal cancer patients." (PMID 22970381, 2012). "In patients with rectal cancer, EGFR is a logical target in combination with neoadjuvant radiotherapy (RT)." (PMID 21437184, 2011). "In retrospective analyses, patients with EGFR-expressing rectal cancer undergoing neoadjuvant RT had a significantly lower DFS and lower chance of achieving a pCR." (PMID 22295206, 2011). "Two types of EGFR inhibitors have been tested in patients with locally advanced rectal cancer in neoadjuvant setting: small-molecule EGFR tyrosine kinase inhibitor (gefitinib) and monoclonal antibody to EGFR (cetuximab)." (PMID 22295206, 2011). "In a trial of 183 patients with local advanced rectal cancer treated with pRCT, only patients with low EGFR expression had TNM downstaging." (PMID 24212803, 2011). "The differences in KRAS mutation rates identified suggest that sex and tumor location influence the chance of clinical usefulness of EGFR inhibitors with a particularly low likelihood of benefit among female rectal cancer patients." (PMID 19832985, 2009). "In conclusion, EGFR is a predictive marker of response to preoperative HDREB in rectal cancers and an independent adverse prognostic factor in MMR-proficient CRC." (PMID 17311026, 2007). "In this study, we again validate this scoring method for EGFR among three independent pathologists in rectal cancer biopsies (ICC=0.71) and TMA punches of CRC (ICC=0.86)." (PMID 17311026, 2007). "The authors analyzed EGFR expression of 45 locally advanced-rectal-cancer patients treated with preoperative radiotherapy and total mesorectal resection." (PMID 15967033, 2005). "Knowledge of expression of EGFR in rectal cancer can contribute to the identification of patients with an increased risk of recurrences." (PMID 15967033, 2005). "In our study, multivariate statistical model identified EGFR expression as a significant independent predictor of recurrence following preoperative and curative surgery for rectal cancer." (PMID 15967033, 2005). "Age, sex, ECOG performance status, RAS mutational status, mismatch repair status, tumour sidedness (right vs. left colon vs. rectal cancer), prior exposure to anti-EGFR or anti-VEGF agents, and prior adjuvant therapy are all presented with hazard ratios (HRs) and 95% confidence intervals (CIs)." (PMID 40563686, 2025). "However, there is limited clinical evidence on FDG-PET/CT for monitoring EGFr inhibitors and tumor regression in patients with rectal cancer after neoadjuvant chemoradiotherapy has been reported." (PMID 41156304, 2025).
rectal cancer (continued). "The most common biomarker-associated therapy recommendation (nine cases) was the use of anti-EGFR therapy for patients with left-sided colon or rectal cancer in the absence of a contraindicating RAS/BRAF mutation." (PMID 39590164, 2024). "Levels of VEGFR3 and EGFR were significantly decreased 5 to 7 months after tumor resection in plasma from 18 surgically resected rectal cancer patients, suggesting that VEGFR3 and EGFR may emanate from tumors." (PMID 34298853, 2021). "However, in our study, a reduced ORR was observed in middle/low rectal cancer treated with anti-EGFR therapy, potentially leading to the unsatisfactory OS in first-line anti-EGFR treatment." (PMID 34188197, 2021). "We next determined whether plasma levels of VEGFR3, EGFR, and COX2 are associated with surgical resection of rectal cancer." (PMID 34298853, 2021). "Some studies have revealed that EGFR-positive rectal cancer cells are more proliferative and infiltrative, which correlate with the TNM stage and LB metastasis, indicating that the high expression of EGFR is associated with the high invasiveness and metastasis of tumours." (PMID 30001205, 2018). "In addition, there are even fewer studies about the correlation of RESOLVE ADC values with the expression of EGFR in rectal cancer." (PMID 30001205, 2018). "In a substantial proportion of patients (46%) we found a discrepancy in EGFR pathway mutations (mainly in KRAS) comparing rectal cancer tissue pre- and post-CRT, which to our knowledge has not previously been described." (PMID 28859058, 2017). "Anti-epidermal growth factor receptor (EGFR) targeted therapy is effective in metastatic rectal cancer, and human epidermal growth factor receptor 2 (HER-2) signaling may mediate resistance to EGFR inhibitors." (PMID 27655166, 2016). "In terms of the predictive response to radiotherapy, several studies have linked epidermal growth factor receptor (EGFR) and vascular endothelial growth factor (VEGF) expression to a lack of response to pre-operative radiotherapy in locally advanced rectal cancer." (PMID 23497522, 2013). "All the data show that EGFR expression, evaluated by IHC, is a predictive factor for poor tumour response and local recurrence after preoperative chemoradiation therapy and curative surgery for rectal cancer." (PMID 20842128, 2010). "Although interrelated, the contribution of VEGF and EGFR to angiogenesis appears to arise through distinct mechanisms, thereby warranting the simultaneous blockade of both proteins for the treatment of patients with rectal cancer." (PMID 18182986, 2008). "Knowledge of expression of EGFR in rectal cancer could contribute to the identification of patients with an increased risk of recurrences, and to the prediction of prognosis." (PMID 15967033, 2005). "The KRAS-mutant rectal cancer organoids showed resistance to the EGFR inhibitor cetuximab, whereas KRAS-wild-type tumoroids displayed sensitivity to this drug, consistent with the clinical trial showing that the KRAS mutation correlates with resistance to EGFR-targeted therapy." (PMID 35551634, 2022). "Interestingly, patients with primary tumors of the caecum derived a substantial disadvantage with anti-EGFR therapy, whereas substantial benefit was seen in patients with rectal cancers and—to a lesser extent —in patients with sigmoid primaries and rather neutral effects were seen in between." (PMID 35158793, 2022). "Therefore, the combination of anti-PD-L1 and EGFR inhibitors may be a potential therapy for RAS wild-type rectal cancer." (PMID 32923389, 2020). "Notably, a novel KRASR68S1 alteration was identified in a 41-year-old female (1.4%) with rectal cancer and synchronous metastases to the liver and retroperitoneal and supraclavicular lymph nodes who experienced PD at 2 months on anti-EGFR therapy with second-line irinotecan + cetuximab." (PMID 28178681, 2017).
rectal cancer (continued). "A study from Iran showed that locally advanced rectal cancer treated with radiotherapy has shown that epidermal growth factor receptor (EGFR) expression may serve as a predictor of pathologic response to treatment and may benefit from more therapeutic modalities." (PMID 23737765, 2013). "Retrospective analyses have demonstrated lower pathologic complete response (pCR) rates and shorter DFS in patients with rectal cancer expressing EGFR who were treated with neoadjuvant RT, suggesting that radiosensitivity might be increased by targeting the EGFR." (PMID 21437184, 2011). "The five most frequently altered potentially targetable genes in colon and rectal cancer were PIK3CA (19.6% and 14.2%), PTEN (8.7% and 5.9%), ERBB2 (4.7% and 6.0%), EGFR (2.5% and 2.0%), and FGFR1 (2.0% and 2.7%)." (PMID 39865537, 2025). "KRAS leads to an epidermal-growth-factor-receptor-independent disturbance of the RAS/RAF/MAPK pathway, which regulates proliferation and survival in rectal cancer." (PMID 36986526, 2023). "For this analysis, VEGFR3, EGFR, and COX2 were assayed in an independent set of plasma consisting of samples collected from 18 rectal cancer patients at the time of diagnosis and 5 to 7 months after surgical resection (pre-and post-surgery RC set)." (PMID 34298853, 2021). "Rectal cancers generally display wild-type RAS genes and are thus often candidates for targeted therapy with EGFR inhibitors." (PMID 32923389, 2020). "The epidermal growth factor receptor (EGFR) pathway contributes to the proliferation, differentiation, and development of a broad spectrum of solid tumors, including rectal cancer." (PMID 32722203, 2020). "In conclusion it seems that AKT1, EGFR, and TP3 are suitable drug targets to prevent rectum cancer progression." (PMID 30774817, 2018). "The presence of MUTKRAS has been recently reported using next generation sequencing analysis of tumor re-biopsies after progression under EGFR-TKI treatment, similarly to colo-rectal cancer treated with EGFR antibodies." (PMID 26799287, 2017). "This Bayesian phase II trial with adaptive randomization was designed to assess the efficacy of adding lapatinib, a dual inhibitor of EGFR and HER-2, to standard radiochemotherapy with capecitabine in stages II and III rectal cancer." (PMID 27655166, 2016). "In conclusion, the LaRRC trial will inform on the role of dual inhibition of EGFR and HER-2 in the neoadjuvant treatment of resectable rectal cancer." (PMID 27655166, 2016). "Chromosome 7 harbors many interesting genes, including druggable targets such as the oncogenes EGFR, BRAF and MET, but at present their relation to the retention of chromosome 7 and the development of local recurrent disease in rectal cancer is unclear." (PMID 26048403, 2015). "In locally advanced rectal cancer (LARC) treated with preoperative chemoradiotherapy (CTRT), baseline EGFR (IHC) expression predicts a poor tumour downstaging and is also an independent prognostic factor for local recurrence." (PMID 20842128, 2010). "We have retrospectively reviewed the baseline EGFR GCN, KRAS status and clinical outcome of 146 locally advanced rectal cancer (LARC) patients treated with preoperative chemoradiotherapy." (PMID 20842128, 2010). "A similar pattern was detectable in rectal cancer, where PIK3CA and PTEN alterations were significantly overrepresented in the RAS/BRAF‐altered subgroup and EGFR, ERBB2, FGFR1, and FGFR3 alterations were significantly overrepresented in the RAS/BRAF‐wt subgroup." (PMID 39865537, 2025).